APP (amyloid beta precursor protein)
Diseases named in the same sentence as APP in open-access papers (continued):
Sharing a sentence is not in itself a finding about the gene and the disease.
osteosarcoma (3 papers, 2023 to 2025). A usually aggressive malignant bone-forming mesenchymal neoplasm, predominantly affecting adolescents and young adults. "In addition, through CellChat analysis,we found that HVECs in osteosarcoma secrete molecules such as MIFand APP, which interact with macrophage surface molecules or complexessuch as CD74 and CD44." (PMID 40834268, 2025). "M2 macrophages communicated with osteoblastic cells via the APP, MIF, and SPP1 signaling pathways, facilitating osteosarcoma development." (PMID 40092698, 2025). "M2 macrophages communicated with osteoblasts by the APP, MIF, and SPP1 signaling pathways, facilitating osteosarcoma development." (PMID 40092698, 2025). "Furthermore, 49 (10.6%) tumors had LOH affecting APP gene(s) in the HLA region (TAP1/2, TAPBP, PSMB8/9, HSPA1A-L), including 14 (20.6%) osteosarcoma and five (22.7%) GBM cases with LOH in both TAP1 and TAP2." (PMID 38318504, 2023).
preeclampsia (3 papers, 2020 to 2024). Preeclampsia is a hypertensive disorder of pregnancy that is characterized by new-onset hypertension with proteinuria presenting after 20 weeks of gestation, and depending on mild or severe forms may initially present with severe headache, visual disturbances, and hyperreflexia. "Human placentas express APP and APP-processing enzymes which are increased in preeclampsia." (PMID 38594674, 2024). "Interestingly, the human placenta abundantly expresses APP and APP-processing enzymes, which are up-regulated in preeclampsia." (PMID 33250783, 2020).
progressive supranuclear palsy (3 papers, 2019 to 2025). A rare late-onset neurodegenerative disease characterized by supranuclear gaze palsy, postural instability, progressive rigidity, and mild dementia. "Searching for other cases resulted in the identification of PSEN1 p.A79V in one possible AD patient, PSEN1 p.R269H and MAPT p.A60G in two independent MCI patients, and GBA1 p.W223R and APP p.A209T in two independent progressive supranuclear palsy (PSP) patients." (PMID 40813364, 2025).
protein (3 papers, 2023 to 2025). "The pathogenesis of amyloid protein starts from the change and cleavage of amyloid precursor protein (APP)." (PMID 36662216, 2023). "Using human fibroblasts with Menkes protein (MNK) deficiency, it has been established that a deficiency of copper notably decreases the levels of APP protein and suppresses the expression of the APP gene." (PMID 40143849, 2025). "We found decreased levels of ROS, Aβ1-40, and Aβ1-42 and increased levels of mitochondrial membrane potential and ATP, which may be associated with PINK1 decreasing oxidative stress and improving energy metabolism disorders in APP/PS1-N2a cells." (PMID 38731398, 2024).
retinal (3 papers, 2012 to 2024). "Our results confirm and expand upon these findings using a new model of the AD retina derived from hiPSC with APP mutations and showing robust retinal AD histopathology at 3 months of differentiation." (PMID 38323188, 2024). "Both APP and Aβ deposits have also been found in the retina of APPswe/PS1 bigenic mouse, we therefore investigated whether CILE-induced retinal lesions are directly associated with retinal accumulation of Aβ." (PMID 22443196, 2012).
rhabdomyosarcoma (3 papers, 2017 to 2018). A rare aggressive malignant mesenchymal neoplasm arising from skeletal muscle. "As endogenous expression of both APP or MstnPP is low in cultured muscle cells, we transduced the human rhabdomyosarcoma cell line CCL 136 with lentivirus coding for human APP, MstnPP or enhanced green fluorescent protein (EGFP)." (PMID 29546591, 2018). "We observed that LC3-II can still be efficiently turned over in autolysosomes of IL-1β and IFN-γ stimulated rhabdomyosarcoma cells, whilst APP turnover was incomplete and led to β-amyloid accumulation." (PMID 28167851, 2017).
Thiamine deficiency (3 papers, 2017 to 2022). Thiamine deficiency is a condition that occurs due to not enough thiamine (vitamin B1). "Thiamine deficiency exacerbates amyloid plaque pathology in Tg19959 transgenic mice, which over express a double mutant form of the amyloid precursor protein-APP." (PMID 36275801, 2022). "In APP/PS1 transgenic mice, the thiamine deficiency induced abnormalities in neurites co-localized with APP-like protein and neurofilament." (PMID 36275801, 2022).
thrombosis (3 papers, 2021 to 2022). "Furthermore, there were also some reported cases of LND developing thrombosis while APP is an important regulator of vein thrombosis and controls coagulation." (PMID 34877405, 2021).
Ventriculomegaly (3 papers, 2017 to 2023). An increase in size of the ventricular system of the brain. "Alternatively, as it is known that APP is upregulated in the presence of free iron, and that iron plays a key role in the pathogenesis of PHH after IVH, it is possible that APP reflects high brain iron levels after IVH in neonates that develop the most severe ventriculomegaly." (PMID 38283681, 2023).
vitamin D deficiency (3 papers, 2017 to 2025). A nutritional condition produced by a deficiency of VITAMIN D in the diet, insufficient production of vitamin D in the skin, inadequate absorption of vitamin D from the diet, or abnormal conversion of vitamin D to its bioactive metabolites. "To confirm the role of APP in driving PTH hypersecretion amid vitamin D deficiency, we compared the secretory responses of parathyroid glands from PTCVdr−/− mice with or without concurrent parathyroid-specific ablation of the App gene (PTCVdr−/−App−/−)." (PMID 40492090, 2025). "In our previous study, analyzing mild vitamin D deficiency, we found increased Aβ peptide level caused by increased β-secretase cleavage of APP and decreased Aβ-degradation in vitamin D deficient mouse brains." (PMID 29257109, 2017). "Recently, we and others could show that vitamin D deficiency causes an increase in amyloidogenic β-secretase cleavage of APP and a decrease in Aβ-degradation, resulting in elevated Aβ level." (PMID 29257109, 2017). "Although vitamin D deficiency was shown to alter APP processing and reduced Aβ degradation, non-neuronal cells may also contribute to the amount of Aβ load." (PMID 36009371, 2022).
Allergy (2 papers, 2012 to 2022). An allergy is an immune response or reaction to substances that are usually not harmful. "Analysis of the levels of APP did not reveal any effect by the chronic allergy, neither in the Balb/c nor in the C57B6 mice." (PMID 22356650, 2012).
Alzheimer’s disease, familial 1 (2 papers, 2021 to 2023). "Autosomal dominant familial early-onset AD (Alzheimer’s disease, type 1) cases are associated with mutations in the gene encoding for the amyloid precursor protein (APP) located on chromosome 21; indeed, at least twenty-five mutations in the APP gene have been related to AD so far." (PMID 35052700, 2021).
ameloblastoma (2 papers, 2022 to 2023). The most common odontogenic tumor, arising from the epithelial component of the embryonic tooth and usually affecting the molar-ramus region of the mandible or maxilla. "With these bioinformatic analyses it is possible that pathogenic ameloblastoma development involve these genes in intracellular regulation (AKT1, ACTC1, ADAM10, and APOA2) or for tumor microenvironment regulation (CRP, BCHE, APP, AGT)." (PMID 36553196, 2022).
Arthritis (2 papers, 2023 to 2024). Inflammation of a joint. "Recent experimental findings demonstrated that inducing arthritis in APP/PS1 mice (a widely recognized model for AD) resulted in increased glial activation and aggravated amyloid deposition." (PMID 39193017, 2024).
Auditory hallucination (2 papers, 2022 to 2025). Perception of sounds without auditory stimulus. "In our study, glutamatergic neurotransmitter pathways were associated with auditory hallucinations, including the APP and GRIA2 genes." (PMID 40943654, 2025).
B cell deficiency (2 papers, 2021). A broad classification of disorders where circulating numbers of B lymphocytes are decreased or ineffective. "Since both 3×TgAD and 3×TgAD-BKO mice express high levels of the APP transgene in hippocampal neurons, we concluded that the benefit of the B-cell deficiency was probably in reduced formation and/or increased clearance of Aβ peptides." (PMID 33846335, 2021).
bacterial meningitis (2 papers, 2020 to 2022). Inflammation of the membranes surrounding the brain and spinal cord due to a bacterial infection. "We and others have previously shown that the expression of both, Fpr1 and Fpr2, is altered in various inflammatory and neurodegenerative animal models including APP/PS1 double-transgenic, in a model of acute, metabolic oligodendrocyte injury, or in a model of bacterial meningitis." (PMID 32331524, 2020).
brain tumor (2 papers, 2016 to 2024). "As a result, we did not test Chol-siRNA or DCA-siRNA against APP/App and do not recommend their use in brain tumor studies (see discussion)." (PMID 38613388, 2024).
CADASIL (2 papers, 2014 to 2022). "Mutations associated with microbleeds in familial conditions include NOTCH-3 in Cerebral Autosomal Dominant Arteriopathy with Subcortical Infarcts and Leukoencephalopathy (CADASIL), APP E693Q and D694N in Dutch-type or Iowa-type CAA, and APP and presenilin mutations in familial AD." (PMID 24432010, 2014).
chronic myeloid leukemia (2 papers, 2011 to 2012). "Gleevec, a cancer drug approved for the treatment of chronic myeloid leukemia, was recently shown to reduce gamma-secretase cleavage for APP." (PMID 21390209, 2011).
Cirrhosis (2 papers, 2020 to 2023). A chronic disorder of the liver in which liver tissue becomes scarred and is partially replaced by regenerative nodules and fibrotic tissue resulting in loss of liver function. "During cirrhosis, the decreased expression of APP and its cleaving enzymes BACE1 and PS1, which are regulated by NO, results in a dramatic intrahepatic decrease of Aβ." (PMID 32089540, 2020).
coronary artery disease (2 papers, 2021 to 2023). "It has been demonstrated that APP and Aβ are increased in plasma of patients with coronary heart disease." (PMID 34531734, 2021).
diabetic encephalopathy (2 papers, 2013 to 2014). A brain disease that is characterized by functional impairment of cognition, cerebral signal conduction, neurotransmission and synaptic plasticity, and underlying structural pathology associated with diabetes. "In the present study, the efficacy of APP 17-mer peptide was evaluated by observing its effect on the electrophysiological changes in diabetic encephalopathy." (PMID 25093193, 2014). "The effect of APP 17-mer peptide on diabetic encephalopathy may be exerted by regulating the metabolism of A β." (PMID 25093193, 2014).
embryonal carcinoma (2 papers, 2016 to 2023). A non-seminomatous malignant germ cell tumor characterized by the presence of large germ cells with abundant cytoplasm resembling epithelial cells, geographic necrosis, high mitotic activity, and pseudoglandular and pseudopapillary structures formation. "It has been reported that hnRNP A1 is involved in alternative splicing of amyloid precursor protein (APP) RNA in neuronal cells differentiated from malignant pluripotent embryonal carcinoma, and increasing hnRNP A1 reduces the formation of Aβ." (PMID 37744386, 2023).
encephalitis (2 papers, 2009 to 2014). An acute inflammatory process affecting the brain parenchyma. "The earlier reports by Nebuloni and colleagues of accumulation of axonal APP in proximity to foci of HIVE have also been confirmed in a simian immunodeficiency virus (SIV) model of encephalitis." (PMID 20028512, 2009). "This is also consistent with pathological documentation of APP accumulation in axons in both HIV encephalitis and a simian immunodeficiency virus (SIV) model of lentivirus encephalitis." (PMID 25541953, 2014).
folate deficiency (2 papers, 2017 to 2021). A nutritional condition produced by a deficiency of FOLIC ACID in the diet. "Mouse brains with folate deficiency presented a reduction in miR-200b-3p, alongside miR-106a-5p and miR-339-5p, eliciting a stimulation of the Amyloid Precursor Protein (APP) gene and the subsequent accumulation of amyloid-β." (PMID 34199498, 2021). "Previous work showed that folate deficiency, a condition associated with HHcy, increases the production of Aβ by affecting SAM‐dependent DNA methylation of genes involved in APP metabolism, such as PS1." (PMID 27896923, 2017).
GNE myopathy (2 papers, 2013 to 2022). "Protein expression was analyzed by serial staining of sections from biopsies of all GNE myopathy patients with immunohistochemical double labeling of 1) APP and MHC-I, 2) αB-crystallin and NCAM, 3) IL-1β and β-amyloid, and 4) iNOS and P-neurofilament." (PMID 23496965, 2013). "Although abnormal Aβ deposition has been found in GNE myopathy, whether APP is abnormal in GNE myopathy is still unknown." (PMID 35904705, 2022).
Leukoencephalopathy (2 papers, 2013 to 2021). This term describes abnormality of the white matter of the cerebrum resulting from damage to the myelin sheaths of nerve cells. "The APP mutations associated with leukoencephalopathy were within the Aβ sequence such as the Iowa mutation, near β-sekretase or γ-sekretase cleavage site." (PMID 34830236, 2021). "Substitution and duplication of APP gene have been also associated with variable white matter abnormalities up to severe leukoencephalopathy." (PMID 24377094, 2013). "Notably, certain APP mutations and duplications have been associated with variable white matter abnormalities up to leukoencephalopathy." (PMID 34830236, 2021). "Interestingly, as previously reported, certain mutations within APP genes presented leukoencephalopathy that should be evaluated on MRI in order to exclude a possible influence of white matter lesions on cognitive decline." (PMID 24377094, 2013).
lung fibrosis (2 papers, 2023). "Among the top differentially expressed genes we found SPARC, LOXL1, and APP which have been implicated in lung fibrosis." (PMID 37085855, 2023).
lysosomal disorders (2 papers, 2010 to 2016). "We have previously demonstrated that a lysosomal storage disorder Niemann-Pick type C (NPC), in which free cholesterol accumulates in late endosomes/lysosomes due to NPC1/NPC2 dysfunction, shows cholesterol-dependent accumulation of intracellular Alzheimer's Aβ and APP-CTF fragments." (PMID 27902765, 2016).
malnutrition (2 papers, 2023 to 2025). Inadequate nutrition resulting from poor diet, malabsorption, or abnormal nutrient distribution. "Furthermore, we found that malnutrition‐worsened affective symptoms in APP/PS1 mice was associated with the downregulation of cAMP signaling pathway in both the midbrain and striatum." (PMID 39868480, 2025). "Furthermore, we aimed to reveal the underlying pathway in the brain regions of interest (ROIs) relevant to the association between malnutrition and NPSs using transgenic APPswe/PSEN1dE9 (APP/PS1) mice." (PMID 39868480, 2025).
mastitis (2 papers, 2011 to 2016). Inflammation of breast tissue during lactation or postpartum due to an obstructed duct or infection. "With the discovery of the major APP in bovine milk and its correlation with mastitis, there has been a growing interest of their exploitation as biomarkers of bovine mastitis which can be adapted to a rapid, on farm measuring format." (PMID 27457305, 2016). "A systemic APP response was detected and cows had mild clinical mastitis." (PMID 21414189, 2011).
meningoencephalitis (2 papers, 2008 to 2015). Inflammation of the meninges and brain, generally secondary to an infectious cause. "However, only one study reported meningoencephalitis in an APP/Tg mouse model passively immunized with repeated injections of high doses of monoclonal anti-Aβ antibodies (1 mg within 16 days)." (PMID 18823564, 2008). "Immunization of F1 SJLxB6 amyloid precursor protein (APP) transgenic (APP-Tg) AD mice with dominant T cell epitope Aβ10-24 stimulated peripheral CD4+ T cell responses but did not result in T cell infiltration nor the occurrence of meningoencephalitis." (PMID 25982697, 2015).
motor neuron degeneration (2 papers, 2013 to 2020). "Considering the contribution of axonal transport deficits in the pathogenesis of motor neuron degeneration, variants in KIF5A disrupt axonal transport and amyloid precursor protein (APP) depletion in the synapse, which causes neurodegeneration." (PMID 33333804, 2020).
myeloma (2 papers, 2023 to 2025). "APP signaling regulates the interaction between myeloma cells and bone marrow stroma through CD74 and CXCR4 receptors, affects the adhesion of myeloma cells to the bone marrow microenvironment, and leads to immune evasion by altering immune cell responses." (PMID 40406148, 2025). "We next looked at the APP signaling network, and the findings indicated that monocyte/macrophages, C3 IGHG4+ myeloma cells, and C0 IGLC3+ myeloma cells had substantial relationships with one another." (PMID 40406148, 2025).
myocardial ischemia (2 papers, 2018 to 2022). A disorder of cardiac function caused by insufficient blood flow to the muscle tissue of the heart. "As has been reported, HN protected neurons against Aβ, okadaic acid-induced neurotoxicity, as well as mutational APP, PS1, and PS2-induced neuronal death in vitro, and also exerts neuroprotection in the model of AD and myocardial ischemia–reperfusion (I/R) injury in vivo." (PMID 30274308, 2018).
non-alcoholic fatty liver disease (2 papers, 2022 to 2024). "In support of this notion, gene profiling of non-alcoholic fatty liver disease (NAFLD) patients showed that APP gene expression in the liver was increased." (PMID 36187787, 2022).
ocular hypertension (2 papers, 2008 to 2025). Abnormally high intraocular pressure. "Another study, also in an animal model demonstrated that the cleavage product of the amyloid precursor protein (APP) (major indicator of AD) is enhanced in ocular hypertension and axonal damage." (PMID 19305795, 2008).